Y_RNA (Y RNA )
Gene: Miscellaneous RNA gene on chromosome 11 (33,171,381 to 33,171,490, reverse strand). Ensembl gene ENSG00000206808.
Homologues: Orthologues: chimpanzee Y_RNA (100% identical), macaque Y_RNA (96% identical). Paralogues in human: RNY1 (90% identical), Y_RNA (88% identical), RNY1P11 (87% identical), Y_RNA (87% identical), Y_RNA (86% identical), Y_RNA (85% identical), RNY1P5 (85% identical), Y_RNA (84% identical), RNY1P7 (83% identical), RNY1P8 (83% identical), Y_RNA (83% identical), Y_RNA (82% identical), and 93 more.